COX7A1 (cytochrome c oxidase subunit 7A1)
Description:
Component of the mitochondrial respiratory complex IV (CIV, also named cytochrome c oxidase complex), the last enzyme in the mitochondrial electron transport chain which drives oxidative phosphorylation (By similarity). The CIV complex is the component of the respiratory chain that catalyzes the reduction of oxygen to water (By similarity). Acts as an assembly factor that specifically drives the homodimerization of CIV complexes, mediating the formation of mitochondrial respiratory supercomplexes (respirasomes) containing two CIV: supercomplxes with two molecules of CIV show improved activity (By similarity). Despite being highly expressed in brown adipose tissue, not required for thermogenesis (By similarity).
Synonyms: COX7AH; COX7A; COX7AM
Tractability: Antibody: UniProt predicts a signal peptide or a membrane-spanning region.
Gene: Protein-coding gene on chromosome 19 (36,150,922 to 36,152,449, reverse strand). Ensembl gene ENSG00000161281.
Subcellular location: Mitochondrion inner membrane
Pathways (Reactome):
Metabolism: Complex IV assembly; Respiratory electron transport
Cellular responses to stimuli: Cytoprotection by HMOX1
Developmental Biology: Transcriptional regulation of brown and beige adipocyte differentiation by EBF2
Gene Ontology:
Molecular function: protein binding; cytochrome-c oxidase activity; protein-macromolecule adaptor activity
Biological process: generation of precursor metabolites and energy; mitochondrial respirasome assembly; oxidative phosphorylation; mitochondrial electron transport, cytochrome c to oxygen; proton transmembrane transport
Cellular component: mitochondrion; mitochondrial inner membrane; mitochondrial membrane; respiratory chain complex; respiratory chain complex IV
Genetic constraint (gnomAD): Loss-of-function variants: 19 observed, 12.59 expected, observed/expected ratio (o/e) 1.51, 90% interval 1.03 to 1.92. The upper end of that interval is the gene's LOEUF score, 1.92, which puts it in group 6 of 6, group 1 being the genes least tolerant of losing a copy. Missense variants: 104 observed, 96.6 expected, observed/expected ratio (o/e) 1.08, 90% interval 0.92 to 1.27. Synonymous variants: 41 observed, 39.32 expected, observed/expected ratio (o/e) 1.04, 90% interval 0.81 to 1.35.
Homologues: Orthologues: chimpanzee COX7A1 (99% identical), macaque COX7A1 (91% identical), dog COX7A1 (84% identical), pig COX7A1 (81% identical), rabbit COX7A1 (76% identical), guinea pig COX7A1 (72% identical), mouse Cox7a1 (71% identical), rat Cox7a1 (68% identical), Drosophila melanogaster COX7AL (38% identical), Drosophila melanogaster COX7AL2 (27% identical). Paralogues in human: COX7A2 (56% identical), COX7A2L (41% identical).
Diseases named in the same sentence as COX7A1 in open-access papers:
COX7A1 is named in the same sentence as 35 diseases in open-access papers, as found by Europe PMC text mining. Sharing a sentence is not in itself a finding about the gene and the disease. The quoted sentences say what the papers report.
non-small cell lung carcinoma (7 papers, 2021 to 2024). A group of at least three distinct histological types of lung cancer, including non-small cell squamous cell carcinoma, adenocarcinoma, and large cell carcinoma. "The lung cancer data, specifically non-small cell lung cancer, the Cox7A1 isoform was investigated, and its elevated level suppresses cell proliferation and colony formation and promotes apoptosis." (PMID 37377864, 2023). "Studies have shown that COX7A1 enhances the sensitivity of non-small cell lung cancer (NSCLC) cells to cysteine-deprivation-induced ferroptosis by promoting TCA cycle activity and the function of mitochondrial complex IV in the ETC." (PMID 38155662, 2023). "Meanwhile, the overexpression of COX7A1 inhibited cell proliferation capacity and colony formation ability of human non-small cell lung cancer cells, which was partly dependent on the regulation of autophagy." (PMID 36418320, 2022). "The relationship between COX7A1 and ferroptosis, a novel form of cell death driven by iron-dependent lipid peroxidation, was further analyzed in different human non-small-cell lung carcinoma (NSCLC) cells respectively." (PMID 36418320, 2022). "COX7A1 acts as a tumor suppressor by inhibiting non-small cell lung cancer’s growth and proliferation by induction of apoptosis via blocking autophagic flux." (PMID 34181336, 2021). "Hspb7, Mb, Cox7a1, Fbp2, and Scara5 have all previously been identified as tumor suppressor genes in breast cancer, non-small cell lung cancer, gastric cancer, sarcoma, and hepatocellular carcinoma, wherein they can suppress tumor cell invasion, proliferation, and migration." (PMID 34194323, 2021). "Recently, it has been found that overexpression of the COX7A1 subunit of COX suppressed the autophagic flux and resulted in the accumulation of autophagosomes in the human non-small cell lung cancer cell line NCI-H838." (PMID 34126926, 2021). "Overexpression of COX7A1 enhances TCA cycle-related enzyme activity and accelerates OXPHOS in human non-small cell lung carcinoma (NSCLC) cells." (PMID 38678018, 2024).
lung carcinoma (6 papers, 2019 to 2025). "The overexpression of COX7A1, a subunit of the cytochrome c oxidase enzyme, was found to render lung cancer cells more susceptible to ferroptosis." (PMID 39811936, 2025). "COX7A1 can increase the sensitivity of lung cancer cells to ferroptosis induced by cysteine deprivation by promoting the activity of tricarboxylic acid cycle and complex IV in mitochondrial electron transport chain." (PMID 38494472, 2024). "At the same time, COX7A1 was found to be able to inhibit lung cancer cell proliferation and colony formation and promote apoptosis." (PMID 38494472, 2024). "COX7A1 has been widely studied in the field of lung cancer, and it has been confirmed that COX7A1 can block autophagy by up-regulating NOX2 and down-regulating PGC-1α." (PMID 38494472, 2024). "Some studies have indicated the anti-cancer potential of COX7A1 in several types of lung cancer cells." (PMID 36418320, 2022). "In this study, human H838 lung cancer cells were tranfected with pCI‐COX7A1 to induce COX7A1 overexpression, and western blot results showed that the expression level of COX7A1 in the Overexpression group was much higher (about 8‐fold) than the Control group." (PMID 31663688, 2019). "Herein, we identified that COX7A1 holds a key position in regulating the development and progression of lung cancer by affecting autophagy." (PMID 31663688, 2019). "Further analysis indicated that the effect of COX7A1 on lung cancer cell viability was partly dependent on the regulation of autophagic flux." (PMID 31663688, 2019). "A better understanding of the detailed function and the related mechanism of COX7A1 in different types of cell and animal models should promote the development of novel and effective methods for lung cancer therapy." (PMID 31663688, 2019). "In this study, we mainly explored the effect of COX7A1 on cell viability and autophagy in human non‐small cell lung cancer cells." (PMID 31663688, 2019). "Our results indicated that the overexpression of COX7A1 suppressed cell proliferation and colony formation ability, and promoted cell apoptosis in human non‐small cell lung cancer cells." (PMID 31663688, 2019). "In conclusion, our study mainly addressed the link between COX7A1 and hallmarks of human non‐small cell lung cancer cells." (PMID 31663688, 2019). "The results showed that the number of colonies in Control group was much higher than the COX7A1 Overexpression group, indicating the inhibitory capability of COX7A1 on the cell viability of human non‐small cell lung cancer cells." (PMID 31663688, 2019). "The results showed that the expression of COX7A1 in cancer tissue was much lower than that in normal lung tissue, suggesting that COX7A1 may inhibit the occurrence and development of lung cancer." (PMID 38494472, 2024). "The relationship between COX7A1 and ferroptosis has also been revealed in lung cancer." (PMID 38494472, 2024). "Hypermethylation of genes such as COX7A1, TNFRSF1B, and BDNF, as well as hypomethylation of genes such as CDC6 and KRT8, may be associated with lung cancer compared to benign nodules." (PMID 39036344, 2024). "In this study, we mainly explored the effect of COX7A1 on the cell viability of lung cancer cells." (PMID 31663688, 2019). "Therefore, our study identified that COX7A1 plays a crucial role in the treatment of human non‐small cell lung cancer." (PMID 31663688, 2019). "However, the ratio of LC3‐II/LC3‐I in the COX7A1 Overexpression groups was much lower than that of the Control group, indicating that COX7A1 might inhibit autophagy in human lung cancer cells." (PMID 31663688, 2019). "Therefore, this research indicated that the low expression of COX7A1 gene may be essential to maintain the cell viability of lung cancer cells." (PMID 31663688, 2019). "Although the crosstalk among COX7A1, PGC‐1α and NOX2 needs our further investigation, our study provides a novel insight into the therapeutic action of COX7A1 against human human non‐small cell lung cancer." (PMID 31663688, 2019).
lung carcinoma (continued). "Although the crosstalk among COX7A1, PGC‐1α and NOX2 needs further investigation, our study provides a novel insight into the therapeutic action of COX7A1 against human non‐small cell lung cancer." (PMID 31663688, 2019). "Besides, we further explored the function of COX7A1 in another non‐small cell lung cancer cell line, NCI‐H1703, and the results were similar to the previous results from H838 cells, indicating the negative regulation effect of COX7A1 on cancer cell viability and autophagy." (PMID 31663688, 2019).
breast carcinoma (3 papers, 2021 to 2022). "Another study demonstrated the downregulation of COX7A1 by promoter hypermethylation in breast cancer." (PMID 34181336, 2021).
dilated cardiomyopathy (3 papers, 2018 to 2023). Cardiomyopathy which is characterized by dilation and contractile dysfunction of the left and right ventricles. "In another mouse study, Cox7a1 KO mice were viable and presented a dilated cardiomyopathy at 6 weeks of age with the Cox7a1 KO mice incorporating more of the “liver-type” isoform of Cox7a2 into the cardiac Cox holoenzyme, translating in higher tissue ATP levels." (PMID 37160609, 2023). "Indeed, the gene is expressed at relatively high levels in muscle cells, consistent with increased demand for OXPHOS, and COX7A1 knockout mice develop a dilated cardiomyopathy." (PMID 29487692, 2018).
gastric cancer (3 papers, 2021 to 2025). A primary or metastatic malignant neoplasm involving the stomach. "COX7A1, a subunit of cytochrome c oxidase, may influence the clinical efficacy of immunotherapy in gastric cancer patients by promoting M2 macrophage differentiation and inhibiting M1 macrophage differentiation." (PMID 40375334, 2025).
lung adenocarcinoma (3 papers, 2019 to 2022). A carcinoma that arises from the lung and is characterized by the presence of malignant glandular epithelial cells. "In 2017, a novel function of COX7A1 was first identified in human lung adenocarcinoma cells." (PMID 31663688, 2019). "Herein, lung squamous cell carcinoma (LUSC) and lung adenocarcinoma (LUAD), two most major subtypes of NSCLC, were chosen to explore the position of COX7A1." (PMID 36418320, 2022). "This suggested that LINC02126 may play important roles in the development of lung adenocarcinoma by regulating the expression of DCN, COX7A1, PLAC9, LUM and MFAP4." (PMID 36357869, 2022). "COX7A1, PLAC9 and LUM are up-regulated in lung adenocarcinoma." (PMID 36357869, 2022).
Obesity (3 papers, 2015 to 2024). Accumulation of substantial excess body fat. "Brain transcriptome analyses in obese mice identified several obesity-related pathways (e.g. leptin, somatostatin, and nemo-like kinase signaling), as well as genes involved in feeding and appetite (e.g. Pmch, Neurotensin) and in metabolism (e.g. Bmp4, Bmp7, Ptger1, Cox7a1)." (PMID 25629159, 2015). "To investigate a putative role of Cox7a1 in BAT-mediated DIT, we subjected WT and Cox7a1-KO mice to a feeding regimen known to induce obesity and impaired glucose tolerance." (PMID 26635001, 2015). "They theorized that the potential anti-obesity effects of taurine might be partly due to thermogenic gene up-regulation in brown adipose tissue, such as UCP-1, Cox7a1, and Cox8b, and fat deposition down-regulation in inguinal white adipose tissue." (PMID 39539444, 2024). "This prompted us to investigate metabolic effects of HFD feeding in WT and Cox7a1-KO mice housed at 31 °C, thus eliminating the need for BAT-derived NST to uncover potential implications of putatively defective BAT-function in the development of diet-induced obesity (DIO)." (PMID 26635001, 2015).
Alzheimer disease (2 papers, 2012 to 2016). A progressive, neurodegenerative disease characterized by loss of function and death of nerve cells in several areas of the brain leading to loss of cognitive function such as memory and language. "Amyloid-b protein deposition in the aged brain of individuals with Alzheimer disease and abnormal expression of the COX7A1 gene, which is involved in glucose metabolism, were previously associated with DNA demethylation and increased age –associated methylation, respectively." (PMID 23285094, 2012).
hepatocellular carcinoma (2 papers, 2018 to 2021). A malignant tumor that arises from hepatocytes. "We observed a statistically significant increase in methylation of the COX7A1 gene in adenocarcinoma, hepatocellular carcinoma and squamous cell carcinoma using publicly available lung methylation data supporting a potential role for DNA methylation in regulating COX7A1 expression in cancer." (PMID 29487692, 2018).
Insulin resistance (2 papers, 2014 to 2015). Increased resistance towards insulin, that is, diminished effectiveness of insulin in reducing blood glucose levels. "It is noteworthy that hypermethylation of the promoter for genes such as PGC-1α, COX7A1, and TFAM may be involved in mitochondrial function and insulin resistance." (PMID 25436770, 2014). "Additionally, factors such as Cox7A1 and TFAM may also lead to mitochondrial dysfunction in insulin resistance." (PMID 25436770, 2014).
sarcoma (2 papers, 2018 to 2021). A usually aggressive malignant neoplasm of the soft tissue or bone. "In all four groups, we observed a statistically significant downregulation of COX7A1 expression in sarcoma cell lines compared to normal adult mesenchymal cells." (PMID 29487692, 2018). "COX7A1 expression level was observed to be undetectable or low in multiple sarcoma and carcinoma cell lines as compared to normal controls." (PMID 29487692, 2018).
atherosclerosis (1 paper, 2020). A disease characterized by the build-up of fatty material and calcium deposition in the arterial wall resulting in partial or complete occlusion of the arterial lumen. "As CIH decreased browning of PVAT, these co-expressed lncRNAs (Gm12251, Gm5421, Gm13910, and KnowTID_00004506) may play an important role in CIH aggravating atherosclerosis by regulating expression of Cox8b, Cox7a1, or Cidea." (PMID 32328084, 2020).
breast tumors (1 paper, 2014). "In our research, expression of marker genes of fat browning, like UCP1, PRDM16, CIDEA, COX7A1, PGC1α, TMEM26 and TBX1, was up-regulated in adipose tissue adjacent to breast tumors." (PMID 25291184, 2014).
Cirrhosis (1 paper, 2023). A chronic disorder of the liver in which liver tissue becomes scarred and is partially replaced by regenerative nodules and fibrotic tissue resulting in loss of liver function. "Additionally, immune infiltration highlighted a strong correlation between macrophages and cirrhosis, with the identifying genes (COX7A1 and IFI27) being significantly associated with macrophages." (PMID 38275754, 2023). "Subsequently, RT-PCR analysis of the liver tissue revealed increased IFI27 and COX7A1 expression in the TAA-treated cirrhosis group compared to the control group." (PMID 38275754, 2023).
depression (1 paper, 2023). "Genes associated with depression or neuro-diseases were found in this study, such as ABCG1, ASMTL, CACNA1F, COX7A1, GRID2, HTR3E, and SHANK2." (PMID 37766304, 2023).
diabetes (1 paper, 2018). "Consistent with its role in metabolism, COX7A1 regulation has been implicated in diabetes and is induced during browning of white adipose." (PMID 29487692, 2018).
endometrial cancer (1 paper, 2026). Primary or metastatic malignant neoplasm involving the endometrium (mucous membrane that lines the endometrial cavity). "Online data analysis revealed that COX7A1 acts as a ferroptosis driver and is significantly downregulated in endometrial cancer tissues." (PMID 41729954, 2026). "In vitro experiments were conducted using cytochrome c oxidase subunit 7A1 (COX7A1) overexpression and knockdown cell lines, followed by ferroptosis-related phenotypic assays to validate the effect of COX7A1 on the inhibition of endometrial cancer cell growth." (PMID 41729954, 2026). "In vitro experiments have demonstrated that overexpression of COX7A1 inhibits the proliferation of endometrial cancer cells and induces ferroptosis by regulating intracellular iron metabolism and mitochondrial function." (PMID 41729954, 2026). "In contrast, knockdown of COX7A1 promotes the proliferation of endometrial cancer cells and inhibits ferroptosis, exhibiting the opposite effects." (PMID 41729954, 2026). "We explore the impact of COX7A1 on mitochondrial dysfunction and ferroptosis in endometrial cancer." (PMID 41729954, 2026).
epithelioid sarcoma (1 paper, 2018). An aggressive malignant neoplasm of uncertain differentiation, characterized by the presence of epithelioid cells forming nodular patterns. "All four osteosarcoma lines showed evidence of an embryonic pattern of low or absent expression of COX7A1, including the epithelioid sarcoma cell line (CRL21380)." (PMID 29487692, 2018).
invasive breast carcinoma (1 paper, 2025). A carcinoma that infiltrates the breast parenchyma. "COX7A1 is involved in mitochondrial metabolism and was identified as a tumor suppressor in invasive breast carcinoma, due to aberrant promoter hypermethylation." (PMID 41048341, 2025).
liposarcoma (1 paper, 2018). A usually painless malignant tumor that arises from adipose tissue. "As in the case of the osteosarcomas, the two liposarcoma cell lines studied, also displayed an embryonic pattern of undetectable COX7A1 gene expression." (PMID 29487692, 2018).